SNORD89 (small nucleolar RNA, C/D box 89)
Synonyms: HBII-289
Gene: Small nucleolar RNA gene on chromosome 2 (101,272,936 to 101,273,049, reverse strand). Ensembl gene ENSG00000212283.
Gene Ontology:
Biological process: RNA processing
Cellular component: nucleolus
Homologues: Orthologues: chimpanzee SNORD89 (100% identical), macaque SNORD89 (97% identical), rat Snord89 (92% identical), rabbit SNORD89 (90% identical), dog SNORD89 (89% identical), mouse Snord89 (88% identical).
Diseases named in the same sentence as SNORD89 in open-access papers:
SNORD89 is named in the same sentence as 6 diseases in open-access papers, as found by Europe PMC text mining. Sharing a sentence is not in itself a finding about the gene and the disease. The quoted sentences say what the papers report.
ovarian carcinoma (2 papers, 2019 to 2022). A malignant neoplasm originating from the surface ovarian epithelium. "In addition, plate clone formation assay showed that overexpression of snoRD126 and snoRD89 significantly increased the number of clone formation in ovarian cancer cells, and the size was larger in OE group." (PMID 35187852, 2022). "The results showed the main roles of SNORD89 in the stemness regulation of ovarian cancer cells." (PMID 31395064, 2019). "Therefore, we speculate that snoRD89 and snoRD126 may affect the prognosis of ovarian cancer by regulating the stem of ovarian cancer cells." (PMID 35187852, 2022).
Arthritis (1 paper, 2022). Inflammation of a joint. "Therefore, we hypothesized that Sema3G upregulates Snord89 to facilitate macrophage proliferation, resulting in aggravation of arthritis." (PMID 35659346, 2022).
endometrial cancer (1 paper, 2025). Primary or metastatic malignant neoplasm involving the endometrium (mucous membrane that lines the endometrial cavity). "For example, SNORD89 is upregulated in endometrial cancer cells, enhancing cancer cell proliferation and migration." (PMID 39794701, 2025).
SNORD89 also shares sentences with these, for which no sentence is quoted: cancer (1 paper); lung disease (1); Sepsis (1).